OR2A7 (olfactory receptor family 2 subfamily A member 7)
Description:
Odorant receptor.
Synonyms: HSDJ0798C17; OR2A21
Tractability: Antibody: its Gene Ontology location is reachable by antibodies, with high confidence; UniProt places it where antibodies can reach, with medium confidence; UniProt predicts a signal peptide or a membrane-spanning region.
Gene: Protein-coding gene on chromosome 7 (144,257,663 to 144,264,792, reverse strand). Ensembl gene ENSG00000243896.
Subcellular location: Cell membrane
Pathways (Reactome):
Sensory Perception: Expression and translocation of olfactory receptors; Olfactory Signaling Pathway
Gene Ontology:
Molecular function: odorant binding; olfactory receptor activity; G protein-coupled receptor activity
Biological process: detection of chemical stimulus involved in sensory perception of smell; G protein-coupled receptor signaling pathway
Cellular component: membrane; plasma membrane
Genetic constraint (gnomAD): Loss-of-function variants: 0 observed, 0.16 expected, observed/expected ratio (o/e) 0, 90% interval 0 to 1.88. That is too few expected variants to judge how well the gene tolerates losing a copy. Missense variants: 25 observed, 142.23 expected, observed/expected ratio (o/e) 0.18, 90% interval 0.13 to 0.25. Synonymous variants: 8 observed, 52.99 expected, observed/expected ratio (o/e) 0.15, 90% interval 0.088 to 0.27.
Homologues: Orthologues: dog OR2A7 (85% identical), mouse Or2a7 (82% identical), rat Or2a7 (81% identical). Paralogues in human: OR2A4 (99% identical), OR2A25 (80% identical), OR2A1 (71% identical), OR2A42 (71% identical), OR2A5 (65% identical), OR2A12 (61% identical), OR2A14 (61% identical), OR2A2 (60% identical), OR7A10 (43% identical), OR1F1 (43% identical), OR7C1 (43% identical), OR1C1 (42% identical), and 116 more.
Diseases named in the same sentence as OR2A7 in open-access papers:
OR2A7 is named in the same sentence as 1 disease in open-access papers, as found by Europe PMC text mining. Sharing a sentence is not in itself a finding about the gene and the disease. The quoted sentences say what the papers report.
carcinoma (1 paper, 2018). A malignant tumor arising from epithelial cells. "OR7E24 and OR2A7 were also expressed, but were not specific to carcinoma tissues in comparison to normal pancreas tissues." (PMID 29497600, 2018).